CPVL (carboxypeptidase vitellogenic like)
Diseases named in the same sentence as CPVL in open-access papers:
CPVL is named in the same sentence as 23 diseases in open-access papers, as found by Europe PMC text mining. Sharing a sentence is not in itself a finding about the gene and the disease. The quoted sentences say what the papers report.
glioma (4 papers, 2021 to 2025). A benign or malignant brain and spinal cord tumor that arises from glial cells (astrocytes, oligodendrocytes, ependymal cells). "Nevertheless, understanding the role of CPVL in glioma progression will improve our understanding of the mechanisms underlying glioma survival, as well as help establish CPVL as a potential therapeutic target for the treatment of glioma." (PMID 34784299, 2021). "Additionally, CPVL has been implicated in glioma, where its high expression in glioma cells is associated with poor prognosis and enhanced glioma cell proliferation." (PMID 39776914, 2024). "Thus, our results provide insight into the molecular mechanism underlying the oncogenic role of CPVL in glioma progression." (PMID 34784299, 2021). "CPVL has been considered as an oncogene that promotes cancer progression, such as glioma and breast cancer." (PMID 39886652, 2025). "Analysis of regulatory effects based on IPA software found that CPVL was involved in the regulation of apoptosis of glioma cells through the IFN-γ/STAT1 signaling pathway." (PMID 34784299, 2021). "Suppressing CPVL expression in glioma cells dramatically enhanced glioma cell apoptosis, suggesting that CPVL activity contributes to sustaining the unwanted survival of glioma cells under the treatment of chemotherapeutics." (PMID 34784299, 2021). "Silencing of CPVL promoted glioma cell apoptosis, and it inhibited cell proliferation and tumorigenicity in vitro and in vivo." (PMID 34784299, 2021). "IPA revealed that the IFN-γ/STAT1 signaling pathway is a downstream target pathway affected by CPVL that results in glioma cell apoptosis." (PMID 34784299, 2021). "CPVL suppressed glioma cell apoptosis by physically interacting with BTK and downregulating the STAT1 phosphorylation through promoting p300-mediated STAT1 acetylation." (PMID 34784299, 2021). "In summary, our results suggest that, as a novel functional gene, CPVL plays a pivotal role in human glioma progression." (PMID 34784299, 2021). "To evaluate the function role of CPVL in glioma cells, we stably knocked down the expression of CPVL by 2 CPVL-specific lentiviral shRNAs (shCPVL#1 and shCPVL#2) in U251 and LN382 cells." (PMID 34784299, 2021). "What’s more, double-staining with antibodies against macrophage marker (CD68) and CPVL proved that the macrophage cell in glioma contributes to the CPVL expression." (PMID 34784299, 2021). "The key findings of our present study are the oncogenic role of CPVL, and CPVL silencing inhibited the cell proliferation and tumorigenicity of glioma." (PMID 34784299, 2021). "What’s more, we also performed the intracranial PDX glioma models to further validate the oncogenic function of CPVL." (PMID 34784299, 2021). "The mRNA level of CPVL in 529 glioma tissues was significantly upregulated compared with 10 normal brain tissues from TCGA database." (PMID 34784299, 2021). "CPVL expression was higher in high-grade (WHO III/IV) glioma compared with low-grade (WHO I/II) glioma." (PMID 34784299, 2021). "Taken together, these results indicate that CPVL silencing inhibited the proliferation and promoted apoptosis of glioma cells to enhance glioma progression." (PMID 34784299, 2021). "Our findings reveal the crucial role of CPVL in promoting the progression of glioma through suppressing STAT1 phosphorylation." (PMID 34784299, 2021). "The oncogenic function of CPVL was further confirmed in the patient-derived xenograft (PDX) mouse models of human glioma." (PMID 34784299, 2021). "IHC staining showed that CPVL expression in glioma tissues was dramatically higher than that in matched adjacent noncancerous tissues." (PMID 34784299, 2021). "CPVL was significantly upregulated in glioma cells and tissues compared with normal cells and tissues, respectively." (PMID 34784299, 2021).
glioma (continued). "To validate the mRNA and protein levels of CPVL in glioma tissues of different grades, we conducted quantitative PCR (qPCR) and Western blotting in the low-grade (WHO I/II) and high-grade (WHO III/IV) glioma groups." (PMID 34784299, 2021). "Taken together, these results show that CPVL silencing induced glioma cell apoptosis via activating STAT1 signaling pathway." (PMID 34784299, 2021). "Collectively, our study demonstrates that CPVL directly interacts with BTK to downregulate the STAT1 phosphorylation through promoting p300-mediated STAT1 acetylation, supporting the pursuit of CPVL as a potential target for glioma intervention." (PMID 34784299, 2021). "Here, we found that CPVL was significantly upregulated in a large cohort of human glioma tissues and that CPVL expression levels were significantly correlated with the clinical characteristics of glioma, including clinical grades." (PMID 34784299, 2021). "Importantly, survival analysis showed that patients with low expression of CPVL had better OS compared with those with high levels of CPVL, suggesting that CPVL is a predictor for survival of patients with glioma." (PMID 34784299, 2021). "These CPVL silencing data prompted us to examine its expression level in more glioma tissues." (PMID 34784299, 2021). "Furthermore, the expression of CPVL in 5 our human glioma tissues was higher than that in matched adjacent noncancerous tissues, which verified the upregulation of CPVL in glioma." (PMID 34784299, 2021). "Chromosome 7 is amplified in glioma, and this may contribute to CPVL overexpression in glioma, suggesting that it is possibly an oncogene." (PMID 34784299, 2021). "Real-time PCR and Western blotting analyses show that CPVL expression was upregulated in 7 glioma cell lines, U87MG, SHG44, LN382, U251, A172, U118, and T98G, compared with the normal glial cell HEB and the human cerebral endothelial cell line HBEC-5i at the transcript and protein levels." (PMID 34784299, 2021). "CPVL silencing compromised the tumorigenicity of glioma cells in vivo." (PMID 34784299, 2021). "CPVL silencing inhibited proliferation and promoted apoptosis of glioma cells in vitro." (PMID 34784299, 2021). "CPVL might serve as a potential prognostic biomarker and therapeutic target for the treatment of glioma." (PMID 34784299, 2021). "In this study, we found that CPVL silencing promoted glioma sensitivity to cell apoptosis." (PMID 34784299, 2021). "CPVL inhibition induced glioma cell apoptosis via the STAT1 signaling pathway." (PMID 34784299, 2021). "Notably, in the current study, we found that CPVL plays an important role in antiapoptosis of glioma that is relatively insensitive to chemotherapy, both in vivo and in vitro." (PMID 34784299, 2021). "The clinical significance and biological role of CPVL in glioma progression, however, remains largely unknown." (PMID 34784299, 2021). "We also demonstrated that downregulating CPVL with CPVL-specific lentiviral shRNAs may be a novel strategy for the treatment of glioma." (PMID 34784299, 2021). "We demonstrate the upregulation of CPVL in both glioma cells and tissues." (PMID 34784299, 2021). "However, CPVL induced apoptosis in glioma cells through the IFN-γ/STAT1 signaling pathway." (PMID 35754804, 2022). "They suggest that CPVL could be a therapeutic target for the treatment of human glioma." (PMID 34784299, 2021). "However, the function of CPVL in various tumors, including glioma, has remained unclear until now." (PMID 34784299, 2021). "In addition, it would be of great interest to know whether other pathways and types of glioma cells could also be modulated by upregulating CPVL." (PMID 34784299, 2021). "The present study has determined that CPVL silencing can significantly activate the IFN-γ/STAT1 signaling pathway, resulting in the apoptosis of glioma cells." (PMID 34784299, 2021).
glioma (continued). "Ingenuity Pathway Analysis (IPA) demonstrated that CPVL silencing activated the IFN-γ/STAT1 signaling pathway, thereby inducing glioma cell apoptosis." (PMID 34784299, 2021). "Full understanding of the precise role of CPVL in human glioma may provide the opportunity to develop a novel therapeutic strategy by suppressing its expression in glioma cells." (PMID 34784299, 2021).
breast carcinoma (3 papers, 2023 to 2025). "Gene set enrichment analysis (GSEA) suggested the potential regulatory pathway of CPVL in breast cancer." (PMID 36825764, 2023). "Inhibiting PTEN activity in breast cancer resulted in CPVL promoting resistance to CDK4/6 inhibitors, and CPVL knockdown decreased the tumorigenicity of CDK4/6 inhibitor‐resistant cells in mice." (PMID 36825764, 2023). "Cell viability, colony formation, cell cycle, and apoptosis assays were used to evaluate the effect of carboxypeptidase vitellogenic like (CPVL) on breast cancer cells under the condition of CDK4/6 inhibitors." (PMID 36825764, 2023). "We found using datasets associated with resistance to CDK4/6 inhibitors in the Gene Expression Omnibus (GEO) that more CPVL was expressed in resistant, than sensitive breast cancer cells, implying a potential role in regulating drug resistance." (PMID 36825764, 2023). "Our findings of viability curves and colony formation showed that CPVL promoted breast cancer cell resistance to CDK4/6 inhibitors." (PMID 36825764, 2023). "We aimed to reveal the mechanism of CPVL in breast cancer resistance to CDK4/6 inhibitors." (PMID 36825764, 2023). "In summary, we revealed the effects of CPVL on resistance to CDK4/6 inhibitors in breast cancer." (PMID 36825764, 2023). "We therefore focused on the role of CPVL in breast cancer resistance to CDK4/6 inhibitors." (PMID 36825764, 2023). "Thus, CPVL knockdown reduced breast cancer cell resistance to CDK4/6 inhibitors in vivo." (PMID 36825764, 2023). "CPVL might be a key factor in regulating breast cancer resistance to CDK4/6 inhibitors." (PMID 36825764, 2023). "Beyond TNBC, we also explored the expression of CPVL and MSR1 in macrophages in other molecular subtypes of breast cancer using bulk RNA sequencing." (PMID 39776914, 2024). "However, the role of CPVL in breast cancer treatment or drug resistance remains unknown." (PMID 36825764, 2023). "The present findings of differentially expressed genes between breast cancer cells that were resistant and sensitive to CDK4/6 inhibitors reveal that CPVL is a potential regulator of drug resistance." (PMID 36825764, 2023). "To investigate whether CPVL and MSR1 have prognostic significance in other intrinsic molecular subtypes of breast cancer, we analyzed their gene expression from 643 patients from the TCGA database." (PMID 39776914, 2024). "More importantly, we found that CPVL promoted drug resistance to CDK4/6 inhibitors by downregulating phosphatase and tensin homolog (PTEN) in vivo and in vitro, indicating that CPVL promotes breast cancer resistance to CDK4/6 inhibitors." (PMID 36825764, 2023).
gastric cancer (3 papers, 2021 to 2024). A primary or metastatic malignant neoplasm involving the stomach. "In previous studies, the relationship between CPVL and macrophages in tumors has only been demonstrated in gastric cancer, where it is positively correlated with M2-like macrophage polarization, contributing to poor patient prognosis." (PMID 39776914, 2024). "Previous studies have shown that CPVL is positively correlated with M2-like macrophage polarization in gastric cancer, which leads to poor prognosis." (PMID 39776914, 2024). "Lastly, we determined the expression of levels of all hub genes in gastric cancer tissues and cell lines, then based on the expression pattern of the genes we selected CPVL to explore its role in cellular proliferation in gastric cancer cell lines." (PMID 35754804, 2022). "We found that high expression of CPVL, ONECUT2, DDC, PRSS21, and GRTP1 increase the risk of gastric cancer." (PMID 35754804, 2022). "We performed the expression of five hub genes in gastric cancers and normal tissue samples which showed significantly high expression of CPVL in cancer samples, and cell lines which was consistent with the RNA sequences obtained from TCGA." (PMID 35754804, 2022). "In gastric cancer cell lines, we showed for the first time that CPVL on cell proliferation, suggesting that CPVL may be a new prognostic target for gastric cancer." (PMID 35754804, 2022). "In gastric cancer cell lines, we determined that CPVL regulate the cellular proliferation, showing that CPVL could be an important predictor in gastric cancer development." (PMID 35754804, 2022). "Here, we conclude that CNVs are key regulators of the immune cells infiltration in gastric TME as well as cancer development, and CPVL could potentially be used as a prognostic and therapeutic marker in gastric cancer." (PMID 35754804, 2022). "The high risk-scores of CPVL, ONECUT2, DDC, PRSS21, and GRTP1 could be used to determine the degree of malignancy and prognosis in gastric cancer patients." (PMID 35754804, 2022). "Moreover, the correlation analyses between CNVs of these genes and immune cell infiltration in gastric cancer identified CPVL as a potential prognostic marker." (PMID 35754804, 2022). "Finally, CPVL showed high expression in gastric cancer samples and cell lines, then siRNA-mediated silencing of CPVL expression in gastric cancer cells showed significant proliferation arrest in MGC803 cells." (PMID 35754804, 2022). "Among five hub genes, we focused on CPVL because it showed the highest degree of correlation with immune cell infiltration and immune checkpoints PD-1/PD-L1 and CTLA-4 in gastric cancer." (PMID 35754804, 2022). "To find out the role of hub genes in the overall survival of gastric cancer we performed a multivariate Cox regression analysis, among 21 hub genes, the eight genes (KCNJ3, CPVL, ONECUT2, SLC19A3, DDC, PRSS21, F12, and GRTP1) were designated as independent indicators of poor prognosis." (PMID 35754804, 2022).
chorioamnionitis (2 papers, 2014 to 2025). A morphologic finding indicating inflammation of the fetal sac membranes. "We also confirmed the several reports of a significant association between cPVL and chorioamnionitis." (PMID 25136457, 2014). "However, meta-regression did not provide conclusive evidence that these differences in GA were correlated with the effect size of the association between cPVL and chorioamnionitis, HDPs, or SGA/IUGR." (PMID 40868516, 2025).
prostate carcinoma (2 papers, 2015 to 2024). A carcinoma that arises from epithelial cells of the prostate gland. "The increased levels of several endosomal/lysosomal peptidases (e.g. cathepsin D, carboxypeptidase Q, probable serine carboxypeptidase CPVL, napsin A) in prostate cancer patients urinary exosomes could be related to cancer progression." (PMID 26196085, 2015).
chordoma (1 paper, 2008). Chordomas are rare malignant tumors arising from embryonic remnants of the notochord in axial skeleton. "This region harbours the genes CREB5, CPVL, and CHN2, none of which has any obvious role in chordoma development." (PMID 18071362, 2008).
epilepsy (1 paper, 2025). A brain disorder characterized by episodes of abnormally increased neuronal discharge resulting in transient episodes of sensory or motor neurological dysfunction, or psychic dysfunction. "The ROC curves revealed that the expression levels of key genes NCAM1, CPVL, PECAM1, and TNC had high accuracy in classifying epilepsy and control groups (AUC >0.9)." (PMID 40520613, 2025).
vitiligo (1 paper, 2024). Generalized well circumscribed patches of leukoderma that are generally distributed over symmetric body locations and is due to autoimmune destruction of melanocytes. "The missense variant in CPVL, seen in LP, is also associated with vitiligo." (PMID 38776927, 2024).
Wilms tumor (1 paper, 2021). An embryonal neoplasm characterized by the presence of epithelial, mesenchymal, and blastema components. "However, Wilms tumors have been linked to deletions or translocations around chromosome 7p15, the region containing the CPVL gene, suggesting that CPVL may act as a tumour suppressor gene." (PMID 34784299, 2021).
cancer (8 papers, 2008 to 2025). A tumor composed of atypical neoplastic, often pleomorphic cells that invade other tissues. "Thus, we comprehensively explored the CPVL in pan-cancer, and its high expression showed a strong association with the poor prognosis in a variety of cancers." (PMID 35754804, 2022). "Total out of 33 pan-cancers, CPVL was found to have high expression in 29 cancers, also showing a significant correlation with the immune and matrix scores." (PMID 35754804, 2022). "Our results indicate the CPVL expressed by macrophages/fibroblasts may also contribute to cancer progression which needs further investigations." (PMID 38962317, 2024). "These genes were presumably involved in cancer (SMG6, HCK), cellular growth (CPVL), reproduction (ADGB, CRISP1, CTTNBP2NL, WDR78), and nervous system (AUTS2, CNTNAP2, CPVL, SRGAP2)." (PMID 40149444, 2025). "This is the first report of methylation in any cancer for five loci (CPVL, HOXC9, PAX8, PTPRN2, and SLC38A4), flagging these loci as potential novel cancer markers." (PMID 18616821, 2008). "Further, five genes, ALMS1, TRAPPC9, CEP128, OR10T2, and CPVL, are among the SCLC genes but not in any of the common cancer gene lists, yet these genes were mutated in M9." (PMID 29050228, 2017). "Among the top 100 gene elements on this axis, we selected 10 candidates, including RAB39A, CPVL, NUP210 and LHX2, which were robustly expressed in cancer cells and CSCs but not in normal MSCs or Fb in both acidic and neutral environments." (PMID 29515775, 2018).
tumor (8 papers, 2018 to 2025). "The tumor weight was decreased in the CPVL-silencing group compared with that in the control group (P < 0.05)." (PMID 34784299, 2021). "CPVL may promote human tumor progression by inhibiting STAT1 pathway through interacting with BTK/p300 axis." (PMID 36479092, 2022). "We found that knockdown of CPVL significantly suppressed tumor growth, as illustrated by decreased tumor growth rates, tumor weights, and Ki-67 and increased cleaved caspase 3 indexes from the shCPVL PDX mouse models compared with that of tumors from the control PDX mouse models (P < 0.05)." (PMID 34784299, 2021). "CPVL inhibition significantly decreased tumor growth rate (P < 0.05)." (PMID 34784299, 2021). "Therefore, CPVL-expressing TAMs may unleash anti-tumor effects by inhibiting SPP1-CD44 and promoting CXCL9-CXCR3 and C3-C3AR1 ligand-receptor reciprocal effects with other cells, like monocytes, neutrophils, and T cells." (PMID 39776914, 2024). "Silencing of CPVL couldn’t significantly affect in vivo tumor growth." (PMID 29515775, 2018). "In our study, we found that the HP infection score in the tumor group was notably higher than that in the normal group and screened five key prognostic genes (CTLA4, CPVL, EMB, CXCR4, and FAM241A) from the HP infection–related DEGs in STAD to establish a riskscore model." (PMID 39886652, 2025). "The TME is a complex ecosystem regulated by multiple interacting pro-tumor and anti-tumor signals, and we have not yet fully elucidated all the specific mechanisms by which CPVL and MSR1 function in TAMs." (PMID 39776914, 2024).
metabolic disease (1 paper, 2025). A congenital disorder (due to inherited enzyme abnormality) or acquired (due to failure of a metabolically important organ) disorder resulting from an abnormal metabolic process. "CPVL gene encodes a serine-like carboxypeptidase involved in protein degradation and immune modulation, affecting inflammatory and metabolic diseases." (PMID 40520613, 2025).
CPVL also shares sentences with these, for which no sentence is quoted: Behçet's disease (1 paper); clear renal cell carcinoma (1); COVID-19 (1); osteoporosis (1); osteosarcoma (1); ovarian carcinoma (1); Pan (1); psoriasis (1); retinopathy (1); triple-negative breast carcinoma (1); type 2 diabetes (1).